RELL2 (RELT like 2)
Description:
Induces activation of MAPK14/p38 cascade, when overexpressed. Induces apoptosis, when overexpressed.
Synonyms: C5orf16; FLJ90583
Tractability: Antibody: UniProt places it where antibodies can reach, with high confidence; UniProt predicts a signal peptide or a membrane-spanning region; its Gene Ontology location is reachable by antibodies, with medium confidence.
Gene: Protein-coding gene on chromosome 5 (141,636,950 to 141,641,064, forward strand). Ensembl gene ENSG00000164620.
Subcellular location: Cell membrane
Subcellular location (Human Protein Atlas): Vesicles
Gene Ontology:
Molecular function: protein binding; collagen binding
Biological process: positive regulation of p38MAPK cascade; positive regulation of cell-substrate adhesion
Cellular component: plasma membrane; basement membrane; extracellular matrix
Genetic constraint (gnomAD): Loss-of-function variants: 18 observed, 29.06 expected, observed/expected ratio (o/e) 0.62, 90% interval 0.43 to 0.92. The upper end of that interval is the gene's LOEUF score, 0.92, which puts it in group 3 of 6, group 1 being the genes least tolerant of losing a copy. Missense variants: 370 observed, 417.08 expected, observed/expected ratio (o/e) 0.89, 90% interval 0.81 to 0.97. Synonymous variants: 156 observed, 157.37 expected, observed/expected ratio (o/e) 0.99, 90% interval 0.87 to 1.13.
Homologues: Orthologues: chimpanzee RELL2 (98% identical), macaque RELL2 (97% identical), rabbit RELL2 (92% identical), pig RELL2 (91% identical), dog RELL2 (90% identical), guinea pig RELL2 (85% identical), mouse Rell2 (85% identical), rat Rell2 (84% identical), tropical clawed frog rell2 (41% identical), zebrafish rell2 (30% identical).
Diseases named in the same sentence as RELL2 in open-access papers:
RELL2 is named in the same sentence as 18 diseases in open-access papers, as found by Europe PMC text mining. Sharing a sentence is not in itself a finding about the gene and the disease. The quoted sentences say what the papers report.
breast carcinoma (4 papers, 2020 to 2023). "It has been found that targeted regulation of RELL2 by microRNA-18a is implicated in the anti-metastatic effect of polyphyllin VI in breast cancer cells." (PMID 37506056, 2023). "RELL2 possesses anti-tumorigenic activities against the breast cancer cell lines 4T1 and 231; treatment of these cell lines with the saponin PPVI upregulates RELL2 expression by relieving the inhibition of mir-18a on RELL2 expression." (PMID 37893069, 2023). "Several reports demonstrated that RELL2 exhibits antitumor activity; for example, RELL2 reduces breast cancer cell invasion and migration and inhibits the tumorigenesis of esophageal cancer cells." (PMID 35634441, 2022). "Previous studies have demonstrated antimetastatic and proapoptotic functions of RELL2 in breast cancer cells and HEK293T cells, respectively, supporting a tumor suppressive role of RELL2." (PMID 32034135, 2020). "Curiously, although experimental evidence demonstrates RELL2 possesses anti-tumorigenic activities in ESCC, PDAC, and breast cancer cell lines, bioinformatic analysis indicates that RELL2 expression is associated with poor outcomes in several cancers." (PMID 37893069, 2023). "Finally, the mouse ortholog of RELL2 promoted the adhesiveness of several cancer cell lines, most notably for the osteosarcoma cell line MG63, consistent with RELL2 functioning to inhibit the migration of tumor cells as was reported for breast cancer cells." (PMID 37893069, 2023).
pancreatic ductal adenocarcinoma (3 papers, 2023 to 2024). An infiltrating adenocarcinoma that arises from the epithelial cells of the pancreas. "RELL2 was previously shown to sensitize pancreatic ductal adenocarcinoma cells to the nucleoside analog gemcitabine, and the ability of RELTfms to sensitize cancer cells to chemotherapy is an avenue that needs further exploration." (PMID 39767574, 2024). "Here, our goal was to analyze the role of receptor expressed in lymphoid tissue (Relt)-like 2 (RELL2) intron 4 retention in promoting pancreatic ductal adenocarcinoma (PDAC) progression." (PMID 37506056, 2023). "Similarly, RELL2 exhibited an anti-tumorigenic effect on pancreatic ductal adenocarcinoma cells in a manner that was dependent on the presence of the RNA splicing factor DHX38." (PMID 39767574, 2024). "Here, we described the role of alternative splicing gene RELL2 and its upstream splicer DHX38 in pancreatic ductal adenocarcinoma." (PMID 37506056, 2023).
leukemia (2 papers, 2023 to 2024). A malignant (clonal) hematologic disorder, involving hematopoietic stem cells and characterized by the presence of primitive or atypical myeloid or lymphoid cells in the bone marrow and the blood. "A separate study indicated higher levels of RELL2 expression are a potential risk factor for leukemia." (PMID 37893069, 2023). "RELL2 expression appeared to be correlated with ECHDC3 in this study, and data suggest that ECHDC3 may increase the chemoresistance of leukemia." (PMID 37893069, 2023).
acute myeloid leukemia (1 paper, 2024). Acute myeloid leukemia (AML) is a group of neoplasms arising from precursor cells committed to the myeloid cell-line differentiation. "Bioinformatic analysis indicates that RELL2 is upregulated and is a poor prognostic indicator for several cancers, and a separate study identified RELL2 as a poor prognostic indicator for acute myeloid leukemia." (PMID 39767574, 2024).
colon adenocarcinoma (1 paper, 2023). "Similarly, higher RELL2 expression was found to correlate with more advanced stages of cancer, higher tumor mutational burden, and/or microsatellite instability in several cancers such as colon adenocarcinoma (COAD)." (PMID 37893069, 2023).
glioblastoma multiforme (1 paper, 2023). "In contrast to the upregulation of RELL1 in glioblastoma, bioinformatic analysis indicates that RELL2 is expressed at lower levels in glioblastoma multiforme (GBM) and low-grade gliomas (LGG) versus normal non-malignant tissues." (PMID 37893069, 2023).
intrahepatic cholangiocarcinoma (1 paper, 2024). A carcinoma that arises from the intrahepatic bile duct epithelium in any site of the intrahepatic biliary tree. "Likewise, a long non-coding RNA molecule expressed from the RELL2 gene was identified as a poor prognostic indicator for intrahepatic cholangiocarcinoma." (PMID 39767574, 2024). "However, long non-coding RELL2 RNA transcripts were identified in intrahepatic cholangiocarcinoma samples, and future experiments are required to further elucidate the function of RNA molecules expressed from the genes of RELTfms." (PMID 39767574, 2024).
Omenn syndrome (1 paper, 2023). An inflammatory condition characterized by erythroderma, desquamation, alopecia, chronic diarrhea, failure to thrive, lymphadenopathy, and hepatosplenomegaly, associated with severe combined immunodeficiency (SCID). "Autoantibodies against RELL2 were unexpectedly observed in many patients with hypomorphic RAG 1/2 mutations, and these autoantibodies targeting RELL2 may potentially contribute to the inflammation observed in patients with Omenn syndrome." (PMID 37893069, 2023).
pancreatic adenocarcinoma (1 paper, 2023). "Bioinformatic analysis by a separate group confirmed that higher RELL2 expression was correlated with increased survival and better patient outcomes for pancreatic adenocarcinoma (PAAD)." (PMID 37893069, 2023).
rectum adenocarcinoma (1 paper, 2022). An adenocarcinoma arising from the rectum. "The highest RELL2 expression was detected in rectum adenocarcinoma (READ) and neck squamous cell carcinoma (HNSC)." (PMID 35634441, 2022).
tumor (6 papers, 2020 to 2024). "We evaluated the associations of RELL2 with six distinct types of immune cells that influence the tumor microenvironment (TME)." (PMID 35634441, 2022). "RELL2 expression was significantly associated with the tumor microenvironment, MSI, and TMB." (PMID 35634441, 2022). "RELL2 can inhibit tumor cell migration and induce the death of cancer cells ex vivo and in vivo, yet it is conversely a poor prognostic indicator for several cancers." (PMID 39767574, 2024). "Previous studies have also demonstrated the anti-tumor role of RELL2 and we got a consistent conclusion through our series of exploration." (PMID 37506056, 2023). "In our study, firstly, we demonstrated the tumor suppressive effect of RELL2 in PDAC through in vitro assays including cell proliferation, cytotoxicity assays and apoptosis." (PMID 37506056, 2023). "To explore the associations of RELL2 with the TME, which contains immune, stromal, and tumor cells, we used the R package of ESTIMATE to determine the immune and stromal scores of every cancer type." (PMID 35634441, 2022). "We then explored RELL2 expression level in tumor cell lines using data from the CCLE (The Cancer Cell Line Encyclopedia) database." (PMID 35634441, 2022). "Our results demonstrated a link between RELL2 expression and immune neoantigens, immune checkpoint genes (ICGs), microsatellite instability (MSI), tumor mutation burden (TMB), and the immune microenvironment." (PMID 35634441, 2022). "Given that TCGA database contains few normal tissues, we merged it with the GTEx database to examine RELL2 expression level in various tumor and adjacent normal tissues." (PMID 35634441, 2022). "Our results identified a correlation of RELL2 with MDSCs, CD4+ T cells, and CD8+ T cells and the correlation of RELL2 with tumor immune infiltration." (PMID 35634441, 2022). "We found that RELL2 expression was significantly correlated with the majority cancers through our pan-cancer analysis and was highly expressed in tumor cells." (PMID 35634441, 2022). "We investigated the possible association of RELL2 with the microsatellite instability (MSI) of various tumors, tumor mutational burden (TMB), immune checkpoint, immune neoantigens, immune microenvironment, and patient prognosis." (PMID 35634441, 2022). "All these data suggest that exon 9-included CCDC15 and exon 3-included RELL2 isoforms are oncogenic and tumor suppressive, respectively." (PMID 32034135, 2020). "Previous studies have shown that RELL2 inhibits tumor progression by promoting apoptosis." (PMID 37506056, 2023). "Additionally, expressing full-length RELL2 with exon 3 reduced the tumorigenic potential of EC109 cells in vivo as determined by xenograft tumor formation in mice." (PMID 37893069, 2023). "RELL2 plays a crucial role in the tumor immune system and induces apoptosis." (PMID 35634441, 2022). "Together, these findings indicate that RELL2 may stimulate tumor progression in many cancer types and lead to an unsatisfactory survival outcome." (PMID 35634441, 2022). "We also found that RELL2 was correlated with the tumor microenvironment and immune cells in many cancers, indicating that RELL2 in the tumor microenvironment and immune cells may regulate the occurrence and development of tumors." (PMID 35634441, 2022). "Moreover, we used the TIMER (Tumor Immune Estimation Resource) database to compare the RELL2 expression level of tumor tissues with that of normal tissue." (PMID 35634441, 2022). "Although ADAR2 is well characterized as a tumor suppressor in several types of cancer, this regulation of RELL2-ex3 inclusion may open up an alternative functional role of ADAR2 in cancer." (PMID 32034135, 2020). "We found that RELL2 expression correlated with increased stages in many cancers, suggesting that high expression level of RELL2 may predict the degree of malignancy of the tumor." (PMID 35634441, 2022).
tumor (continued). "We investigated the expression level of RELL2 through several databases such as TCGA, CCLE, GTEx, and TIMER and found that RELL2 is overexpressed in many tumor tissues." (PMID 35634441, 2022). "To understand the functional importance of ADARs-mediated splicing changes in cancer, we examined the splicing pattern of CCDC15-ex9 and RELL2-ex3 in 33 matched pairs of primary ESCC and non-tumor (NT) samples." (PMID 32034135, 2020).
cancer (5 papers, 2020 to 2025). A tumor composed of atypical neoplastic, often pleomorphic cells that invade other tissues. "RELL2 is poorly associated with the prognosis of several cancers and is strongly associated with the expression of immune checkpoints." (PMID 41376629, 2025). "Expression of RELL2 was associated with decreased overall survival, disease-specific survival, and/or progression-free interval for several cancers, including adenoid cystic carcinoma, kidney chromophobe (KICH), and uterine carcinosarcoma." (PMID 37893069, 2023). "In this study, we performed an exhaustive pan-cancer analysis to examine the possible role of RELL2 in cancers and the associations of its expression with prognosis." (PMID 35634441, 2022). "RELL2 expression is linked with worse progression-free interval and overall survival in numerous cancers." (PMID 35634441, 2022). "We next examined the association of RELL2 expression with pathological stage in pan-cancers, MSI, and TMB status from the TCGA database." (PMID 35634441, 2022). "This study unveils the mechanism underlying RELL2 in pan-cancer according to the data obtained from various datasets." (PMID 35634441, 2022). "Interestingly, RELL2 expression in tumors was associated with the expression of several checkpoint inhibitors in several cancers including TNFRSF25 (DR3)." (PMID 37893069, 2023). "Although this bioinformatic data do not always indicate causation, there remains the possibility that RELL2 may function in a pro-tumorigenic manner in some cancers, and in an anti-tumorigenic manner in separate cancers." (PMID 37893069, 2023). "RELL2 expression is strongly associated with phenotypes that are of major clinical significance, particularly those associated with immune neoantigens and the expression profiles of immune checkpoint genes in pan-cancer." (PMID 35634441, 2022). "RELL2 exhibited relatively consistent levels of expression across all cell lines, albeit with less protein expressed in Thp1 cells compared to the other cancer cell lines tested." (PMID 39767574, 2024). "The cancers in which RELL2 expression appeared to correlate the strongest with different checkpoint molecules included KICH, thymoma, and kidney renal clear cell carcinoma." (PMID 37893069, 2023). "RELL2 was expressed at higher levels in 16 out of the 20 cancers analyzed, with the highest expression levels in rectum adenocarcinoma and HNSC." (PMID 37893069, 2023). "We then explored the relationships between RELL2 and different immune checkpoints and found that RELL2 was significantly expressed in many cancers." (PMID 35634441, 2022). "The findings demonstrated the significant correlation of RELL2 expression level with the expression of several checkpoint genes in different cancer types, particularly KICH, KIRC, and THYM." (PMID 35634441, 2022). "We further explored the prognostic value of RELL2 by analyzing the association of RELL2 expression with OS, DSS, DFI, and PFI in various cancer types." (PMID 35634441, 2022). "Our findings demonstrated that RELL2 was correlated with immune cells in different cancer types, particularly in KIRC and LIHC." (PMID 35634441, 2022). "The three leading cancer types that were significantly correlated with the RELL2 expression and immune score deduced using ESTIMATE were LAML, LGG, and LUSC." (PMID 35634441, 2022). "A large sample size and comprehensive analysis of RELL2 can provide insight for future exploration of the role of RELL2 in cancer." (PMID 35634441, 2022). "We investigated RELL2 expression level in pan-cancer data from the TCGA (The Cancer Genome Atlas) dataset and found that RELL2 was expressed higher in 16 out of 20 cancers." (PMID 35634441, 2022). "Collectively, these results identify RELL2 as a potential prognostic biomarker for various cancer types." (PMID 35634441, 2022). "We classified all pan-cancer samples into the low- and high-expression groups using the median expression level of RELL2." (PMID 35634441, 2022).
cancer (continued). "Subsequent survival analysis revealed that the overexpression of RELL2 predicted a poor survival outcome of cancer patients." (PMID 35634441, 2022). "There have been many reports highlighting the anti-cancer activities of saponins produced by this plant (the Chinese name of the plant is Chonglou), and upregulation of the anti-cancer properties of RELL2 via PP-VI should be further explored as a potential treatment for BC." (PMID 39767574, 2024). "It is interesting to speculate whether therapeutics that promote RELL2 transcript stability and translation may help with the treatment of cancers." (PMID 37893069, 2023). "In most cancers, high RELL2 expression was related to a poor prognosis." (PMID 35634441, 2022). "In our study, we found that RELL2 is overexpressed in most cancers." (PMID 35634441, 2022). "High expression of RELL2 correlates with a poor prognostic outcome in most cancers." (PMID 35634441, 2022). "RELL2 is highly expressed in cancer compared with normal tissues." (PMID 35634441, 2022). "RELL2 may be a prognostic biomarker in pan-cancer and may have an important function in tumorigenesis and progression." (PMID 35634441, 2022). "RELL2 was expressed higher in 18 out of 27 or in the majority of cancer types." (PMID 35634441, 2022). "The results showed RELL2 plays an independent role in many cancers." (PMID 35634441, 2022). "However, whether RELL2 contributes to cancers remains unclear." (PMID 35634441, 2022). "RELL2 expression level was significantly correlated with TMB in UCEC, THYM, COAD, and CESC and significantly correlated with MSI in 16 cancer types, including UCEC, THCA, PRAD, LUSC, LUAD, HNSC, COAD, and BRCA." (PMID 35634441, 2022).
neurological disorders (1 paper, 2023). "There are currently no additional studies suggesting a link between RELL2 and neurological disorders, yet it should be noted that the HPA predicts a higher expression of RELL2 in the brain than either PCDHGB6 or FCHSD1." (PMID 37893069, 2023).
RELL2 also shares sentences with these, for which no sentence is quoted: esophageal cancer (1 paper); lung carcinoma (1); osteosarcoma (1); pancreatic cancer (1); periodontitis (1).